ESRP1 (epithelial splicing regulatory protein 1)
Description:
mRNA splicing factor that regulates the formation of epithelial cell-specific isoforms. Specifically regulates the expression of FGFR2-IIIb, an epithelial cell-specific isoform of FGFR2. Also regulates the splicing of CD44, CTNND1, ENAH, 3 transcripts that undergo changes in splicing during the epithelial-to-mesenchymal transition (EMT). Acts by directly binding specific sequences in mRNAs. Binds the GU-rich sequence motifs in the ISE/ISS-3, a cis-element regulatory region present in the mRNA of FGFR2. Regulates splicing and expression of genes involved in inner ear development, auditory hair cell differentiation, and cell fate specification in the cochlear epithelium (By similarity).
Synonyms: RBM35A; FLJ20171; DFNB109; RMB35A
Tractability: PROTAC: ubiquitination databases record sites on it.
Gene: Protein-coding gene on chromosome 8 (94,640,987 to 94,707,466, forward strand). Ensembl gene ENSG00000104413.
Subcellular location: Nucleus
Subcellular location (Human Protein Atlas): Nuclear bodies; Nucleoplasm
Pathways (Reactome):
Disease: Signaling by BRAF and RAF1 fusions
Signal Transduction: FGFR2 alternative splicing
Gene Ontology:
Molecular function: mRNA binding; protein binding; nucleic acid binding; RNA binding
Biological process: regulation of RNA splicing; regulation of inner ear auditory receptor cell fate specification
Cellular component: nuclear body; nucleoplasm; nucleus; ribonucleoprotein complex
Genetic constraint (gnomAD): Loss-of-function variants: 19 observed, 62.71 expected, observed/expected ratio (o/e) 0.3, 90% interval 0.21 to 0.44. The upper end of that interval is the gene's LOEUF score, 0.44, which puts it in group 1 of 6, group 1 being the genes least tolerant of losing a copy. Missense variants: 527 observed, 688.4 expected, observed/expected ratio (o/e) 0.77, 90% interval 0.71 to 0.82. Synonymous variants: 258 observed, 258.24 expected, observed/expected ratio (o/e) 1, 90% interval 0.9 to 1.11.
Gene-disease validity (ClinGen):
ClinGen rates the evidence that ESRP1 causes each of these diseases.
nonsyndromic genetic hearing loss (autosomal recessive): Limited.
Homologues: Orthologues: chimpanzee ESRP1 (100% identical), macaque ESRP1 (99% identical), rabbit ESRP1 (98% identical), pig ESRP1 (97% identical), mouse Esrp1 (97% identical), dog ESRP1 (97% identical), rat Esrp1 (97% identical), guinea pig ESRP1 (96% identical), tropical clawed frog esrp1 (86% identical), zebrafish esrp1 (66% identical), Drosophila melanogaster fus (46% identical), Caenorhabditis elegans sym-2 (33% identical), and 3 more. Paralogues in human: ESRP2 (60% identical), HNRNPH1 (19% identical), HNRNPH2 (19% identical), HNRNPF (18% identical), GRSF1 (17% identical), RBM12B (15% identical), RBM12 (13% identical), HNRNPH3 (13% identical).
Diseases named in the same sentence as ESRP1 in open-access papers:
ESRP1 is named in the same sentence as 90 diseases in open-access papers, as found by Europe PMC text mining. Sharing a sentence is not in itself a finding about the gene and the disease. The quoted sentences say what the papers report.
breast cancer (74 papers, 2011 to 2025). A primary or metastatic malignant neoplasm involving the breast. "As a result of alternative splicing, ZMYND8 exon 22 inclusion was linked to a better prognosis in breast cancer patients, enhanced by hnRNPM and opposed by Epithelial Splicing Regulatory Protein 1 (ESRP1)." (PMID 38539439, 2024). "Higher levels of ESRP1 expression have been detected in breast cancer, and have been associated with poor prognosis in oestrogen receptor positive breast cancer cells." (PMID 37752235, 2023). "In breast cancer, the reduction of ESRP1 changes the variant expression of CD44v from CD44v to CD44, thus inhibiting its metastasis in the lung." (PMID 36052258, 2022). "In breast cancer, reduction of ESRP1 changes the variant expression from CD44v to CD44s and inhibits metastasis to the lung." (PMID 32967226, 2020). "PSFs such as GRHL2 associate with poor prognosis in breast cancer, motivating us toinvestigate the correlation of ESRP1 with patient survival rates." (PMID 31069317, 2018). "Clinically, we found that ESRP1 expression was positively associated with circANKS1B expression in breast cancer tissues (r = 0.626, n = 165, p < 0.001)." (PMID 30454010, 2018). "Low ESRP1/RBFOX2 ratio value was associated with a higher risk of metastasis (p < 0.005) in early breast cancer patients, regardless other clinical features." (PMID 27911856, 2017). "Of these, expression of IFI16 and ANKD1 were particularly strongly associated with RAB25 and ESRP1 levels in primary breast cancer." (PMID 26646320, 2016). "Our result of decreased CD44v splice variants in CRC tumor cells are supported by findings in metastatic breast cancer cells that changed the expression from CD44v to CD44s variant isoforms on the cell surface after depletion of ESRP1." (PMID 27650542, 2016). "In breast cancer patients ESRP1 was associated with lower patient survival rate, in contrast to pancreatic ductal adenocarcinoma where increased ESRP1 expression was related to better survival." (PMID 27650542, 2016). "This is in agreement to pancreatic ductal adenocarcinoma where increased ESRP1 expression was related to better survival, but in contrast to breast cancer patients where ESRP1 was associated with lower survival rate." (PMID 27650542, 2016). "Understanding the specific mechanism of ESRP1 in breast cancer may help develop new diagnostic and therapeutic approaches." (PMID 40046628, 2025). "In fact, the association of low ESRP1/ RBFOX2 ratio with high risk of metastasis in early breast cancer was speculated to be a new early prognostic marker of breast cancer metastasis." (PMID 31737791, 2019). "ESRP1 expression in 4T1 breast cancer cells has been shown to enhance their metastatic potential and high ESRP1 expression is associated with poor survival of breast cancer patients." (PMID 28052020, 2017). "Moreover, their investigation in fresh primary tumor tissue from patients with early breast cancer revealed that a low ESRP1/RBFOX2 ratio value was significantly associated with a high risk of metastasis in early breast cancer." (PMID 27911856, 2017). "Furthermore, favorable overall survival of breast cancer patients was associated with low ESRP1 expression." (PMID 27650542, 2016). "RBFOX2 plays a dual role, acting as an important co-regulator of ESRP1 in epithelial phenotype cells and as an interstitial-specific splicing factor in more invasive breast cancer subtypes." (PMID 40046628, 2025). "ESRP1 promotes tumor progression in ER+ breast cancer cells by regulating genes involved in fatty acid/lipid metabolism and oxidative reduction processes." (PMID 40046628, 2025). "Hypoxia-driven ESRP1 deletion induces skipping of hMENA Exon 11a, producing the pro-migratory isoform hMENAΔ11a, which promotes breast cancer EMT through the TGF- RBFOX2-ESRP1 axis." (PMID 40046628, 2025).
breast cancer (continued). "Overall, the role of ESRP1 in breast cancer is mainly through the regulation of gene splicing, affecting the behavior of tumor cells and the tumor microenvironment, thereby influencing the occurrence, development, invasion, and metastasis of breast cancer." (PMID 40046628, 2025). "Recent studies have shown that the expression level of ESRP1 is closely related to the occurrence, development, and prognosis of breast cancer." (PMID 40046628, 2025). "ESRP1, by regulating the expression of CD44 splice variants, can influence the behavior of tumor cells, significantly impacting the EMT process and breast cancer metastasis." (PMID 40046628, 2025). "Increasing evidence has demonstrated that ESRP1 dysregulation is closely correlated with the tumorigenesis and progression of various types of cancers, including ovarian cancer, breast cancer, prostate cancer, colorectal cancer, lung cancer and so forth." (PMID 40528239, 2025). "It was found to target the ESRP1 gene in breast cancer cells, leading to suppression of migration and invasion." (PMID 39595529, 2024). "ESRP1 has been reported as controlling ER+ breast cancer, and ESRP1/ESRP2 were noted as being the most strongly down-regulated RBPs in epithelial-to-mesenchymal transition (EMT) in a cell culture model of breast cancer." (PMID 38838009, 2024). "ESRP1 downregulation enhanced invasion of breast cancer cells by promoting the generation of hMENAΔ11a isoform, which results in the mesenchymal phenotype." (PMID 38110955, 2023). "ESRP1 protein regulates splicing of the CD44 cell surface receptor mRNA, that encodes a protein which interacts with tyrosine kinases in breast cancer cells." (PMID 37752235, 2023). "ESRP1 is controlled by the steroid hormone receptor ERα in breast cancer cells, and there are ERα binding sites within ESRP1 and ESRP2 promoters." (PMID 37752235, 2023). "ESRP1 is also controlled by the transcription factor E2F1 in breast cancer cells and sensitive to oxygen levels." (PMID 37752235, 2023). "ESRP1/2 have been shown to be down- or upregulated in breast cancer as well as oral/head and neck cancer." (PMID 38110955, 2023). "In their subsequent study, the authors showed that coregulation of alternative splicing by hnRNPM and ESRP1 is widespread and primarily antagonistic in breast cancer cells, although a subset of events is regulated concordantly." (PMID 38106992, 2023). "A transient knockdown of ESRP1 in human breast cancer MCF7 and human pancreatic adenocarcinoma BxPC-3 cells resulted in a shift of expression from CD44v (containing exon v6) to CD44 isoform 4 without affecting total CD44 level." (PMID 38106992, 2023). "ESRP1 has been reported to affect the growth of estrogen receptor (ER)-positive breast cancer by regulating cellular metabolism (fatty acid and lipid metabolism)." (PMID 38110955, 2023). "Alternative splicing of CD44 under the control of splicing factor ESRP1 has been shown to increase migration and lead to metastasis in breast cancer, ovarian cancer, and melanoma." (PMID 37457440, 2023). "In breast cancer, analysis of the Gene Expression Omnibus database revealed that high ESRP1 expression is correlated with significantly shorter overall survival in patients with breast cancer." (PMID 38110955, 2023). "Further studies are warranted to validate the prognostic value and role of ESRP1 in subtypes of breast cancer." (PMID 38110955, 2023). "Vice versa, overexpression of ESRP1 in undifferentiated, mesenchymal breast cancer MDA-MB231 cells and pancreatic ductal adenocarcinoma Panc-1 cells resulted in a reverse isoform switch accompanied by decreased ZEB1 levels." (PMID 38106992, 2023). "When the miR-101-5p-associated pathways in breast cancer were assessed using RNA-seq, a particular group of genes, HMGB3, ESRP1, GINS1, TPD52, SRPK1, VANGL1, and MAGOHB, were suggested to be associated with a poor prognosis of BC." (PMID 38132441, 2023).
breast cancer (continued). "Consistent with the prognostic significance of ESRP1 in breast cancer, ESRP1 was demonstrated to promote lung metastasis in orthotopic mouse model of breast cancer by regulating alternative splicing of CD44 mRNA." (PMID 38110955, 2023). "ESRP1 was also found to suppress breast cancer stem cell function by promoting CD44 splice isoform switching from CD44s isoform that causes stemness to CD44v isoform." (PMID 38110955, 2023). "For example, in breast cancer cells, ESRP1 regulated the expression of CD44v and silencing ESRP1 in CD44v+ cells led to a switch from CD44v to CD44s isoform, leading to inhibition of lung cancer metastasis." (PMID 36678534, 2022). "It was shown that ESRP1 promotes lung cancer metastasis by regulating CD44 splicing in ER-negative 4T1 mouse mammary tumor cells." (PMID 36052258, 2022). "In breast cancer cells, knockdown of ESRP1 (Epithelial Splicing Regulatory Protein 1) decreased the expression of fatty acid, lipid metabolism targets and oxidoreductases including PHGDH (D-3-phosphoglycerate dehydrogenase)." (PMID 35565242, 2022). "Our findings provide previously unreported mechanistic insights into the plastic nature of ESRP1 expression and insinuate important implications in therapeutics targeting breast cancer progression." (PMID 34362878, 2021). "To examine the mRNA and protein expression pattern of ESRP1 in breast cancer, we analyzed The Cancer Genome Atlas (TCGA) and the Clinical Proteomic Tumor Analysis Consortium (CPTAC) data using the UALCAN platform." (PMID 34362878, 2021). "Studies also showed that ESRP1 promotes breast cancer metastasis by regulating CD44 mRNA alternative splicing." (PMID 33483472, 2021). "At the same time, breast cancer patients with high expression of ESRP1 also have a poor overall survival." (PMID 34439339, 2021). "Previous studies have indicated that epithelial splicing regulatory protein 1 (ESRP1) negatively regulates EMT in breast cancer, PC, oral squamous cell carcinoma, and non-small cell lung cancer." (PMID 34828307, 2021). "Knockdown of the epithelial splicing regulatory protein 1 in endocrine-resistant breast cancer models significantly decreases growth." (PMID 34356101, 2021). "Collectively, our study dissects previously unreported mechanistic insights into the expressional plasticity of ESRP1 during breast cancer progression and alludes to important therapeutic interventions." (PMID 34362878, 2021). "ESRP1 plays an important role in chemoresistance of various cancers, including breast cancer, colon cancer and non-small cell lung cancer." (PMID 33495408, 2021). "On the other hand, in a previous study, we have reported that ESRP1 expression is drastically ablated in the hypoxic regions of breast cancer tissues." (PMID 34362878, 2021). "By analyzing TCGA databases, we also observed a similar overexpression of ESRP1 in breast carcinoma as against normal breast tissues." (PMID 34362878, 2021). "Our results reveal that an elevated expression of transcription factor E2F1 and increased CpG hydroxymethylation of the E2F1 binding motif conjointly induce ESRP1 expression in breast carcinoma." (PMID 34362878, 2021). "Previous studies have shown that in patients with ER (Estrogen Receptor) positive breast cancer, OS was significantly shorter in the high ESRP1 group." (PMID 32467669, 2020). "Up-regulating ESRP1 in the mesenchymal breast cancer cell line, MDA-MB-231, resulted in a significantly higher expression of the short subtype of EPB41L5." (PMID 32467669, 2020). "Considering that ESRP1 is proposed as a master proto‐oncogenic mRNA splicing regulator responsible for CD44 alternative splicing in breast cancer, we did further genetic rescue experiments." (PMID 33240752, 2020). "hnRNP M can enhance breast cancer metastasis by stimulating the expression of mesenchymal specific CD44v via a competitive interaction with ESRP1." (PMID 32967226, 2020).
breast cancer (continued). "By contrast, cells that express low levels of ZEB1/2 along with high levels of ESRP1/2 and E-cadherin were categorized into the “luminal” subtype of breast cancer with relatively good prognosis." (PMID 31682640, 2019). "We also previously reported that ZEB1/2 are preferentially recruited to the promoter region of ESRP1 where they suppress the transcription of ESRP1 in breast cancer cells." (PMID 31682640, 2019). "And a positive correlation between USF1 and ESRP1 expression was observed in breast cancer tissues from TCGA database (r = 0.264, n = 1109, p < 0.001)." (PMID 30454010, 2018). "We found that ESRP1 levels were lower in high-LYNA breast cancers as a whole and in the high-LYNA TNBC subset." (PMID 30590041, 2018). "Here, we identified a splicing factor, ESRP1, was involved in circANKS1B biogenesis in breast cancer." (PMID 30454010, 2018). "It has been shown that depletion of ESRP1 in metastatic breast cancer cells changed the phenotype of these cells from CD44v to CD44s, and resulted in the suppression of lung metastasis." (PMID 30112117, 2018). "And breast cancer patients with high ESRP1 expression displayed poor overall survival (p < 0.001) and distant metastasis-free survival (p < 0.001)." (PMID 30454010, 2018). "Taken together, our data indicate that ESRP1 drives switching from mesenchymal to epithelial phenotype by regulating alternative splicing in OC cells, similar to its function in breast cancer cells, suggesting that ESPR1 has similar roles in breast and OC." (PMID 28991261, 2017). "The ratio ESRP1/RBFOX2 showed fairly high specificity in discriminating between breast cancer tissue from NED patients and that from MET patients, with an area under ROC curve (AUC) of 0.8375 (95% CI 0.6963–0.9787)." (PMID 27911856, 2017). "The results provide a rationale for using ESRP1/RBFOX2 ratio as a new prognostic biomarker for the early prediction of metastatic potential in breast cancer." (PMID 27911856, 2017). "We also repeated the assays in the SCP28 breast cancer cell line and found that ESRP1 overexpression also led to CD44 isoform switching and elevation of lung metastasis, but not affecting the CSC feature of the cells." (PMID 28300837, 2017). "Increasing or reducing the CD44v/CD44s ratio of breast cancer cells by regulating the expression of epithelial splicing regulatory protein 1 (ESRP1) leads to promotion or suppression of lung metastasis without influencing cancer cell stemness." (PMID 28300837, 2017). "ESRP1 and 2 expression has been further recognized to be implicated in EMT-associated splicing programs in breast cancer." (PMID 22069487, 2011). "have shown that ESRP1 affects tumor progression in ER+ breast cancer cells by regulating genes involved in fatty acid/lipid metabolism and oxidation-reduction processes, and that high expression of ESRP1 is associated with poor prognosis in estrogen receptor-positive (ER+) breast tumors." (PMID 40046628, 2025). "Research shows that abnormal expression of ESRP1 is closely related to the formation and development of various solid tumors, including breast cancer, lung cancer, stomach cancer, and others, and is closely associated with the invasiveness, metastasis, and poor prognosis of tumors." (PMID 40046628, 2025). "Furthermore, clinical data showed that ESRP1 expression levels were positively correlated with patient survival in clear cell renal cell carcinoma and breast cancer." (PMID 40528239, 2025). "Double knockdown of δEF1 and SIP1 increased the mRNA levels of ESRP1 in human breast cancer cells." (PMID 38110955, 2023). "Notably, ESRP1 regulated breast cancer stem cell properties by determining the expression of stemness-inducing α6B variant relative to α6A variant." (PMID 38110955, 2023). "miR-337-3p inhibited breast cancer cell migration and invasion by downregulating ESRP1." (PMID 38110955, 2023).